CD44 (CD44 molecule (IN blood group))
Diseases named in the same sentence as CD44 in open-access papers (continued):
Sharing a sentence is not in itself a finding about the gene and the disease.
tumor (continued). "The CD44 gene contains 20 exons that are alternatively spliced, giving rise to many CD44 isoforms, perhaps including tumor-specific sequences." (PMID 21749678, 2011). "By contrast, Du145-WP1102 cells, which retained some tumor-initiating capacity, showed similar levels of CD44 protein expression to or slightly more CD44+ (many faintly positive) cells than parent Du145 cultures." (PMID 21935404, 2011). "Our recent work shows that Nanog, essential for the self-renewal and pluripotency of ES cells, is enriched in the CD44+ PCa cell population and functionally required for tumor development." (PMID 21935404, 2011). "Tissue microarray containing 64 tumor samples from 37 patients was performed to assess any correlation between pan-CD44 protein expression and the overall survival of the affected patients." (PMID 21915300, 2011). "E/M-MP cells are enriched for tumor-forming cells and express both epithelial and mesenchymal markers (cytoplasmic E-cadherin, CD44) as well as high levels of the putative cancer stem cell marker CD133." (PMID 21264259, 2011). "A significant association was also found between the percentage of CD44+ cells and BRCA1 defective tumours (p<0.001)." (PMID 23508738, 2011). "When overexpressed in tumor cells, soluble CD44 can function as an antagonist to cell membrane CD44 and block its binding to ECM HA." (PMID 22216242, 2011). "CD44 sorted tumor cell populations have been reported to be enriched for tumorigenic and metastatic progenitor cells." (PMID 24212937, 2011). "The CD44+CD24-/low cells were able to form tumours in NOD/SCID mice from fewer cells than the mixed population with 10- to 50-fold enrichment for this ability." (PMID 22112299, 2011). "H&E staining of CD44+CD24+ESA+ CSC tumors formed in nude mice revealed similar tumor phenotype with that of primary human tumors." (PMID 21304978, 2011). "Tumours with a CD44+/CD24- phenotype are highly invasive with targeted reduction of CD44 markedly reducing malignant characteristics of tumours in vivo." (PMID 21713035, 2011). "Other reports have indicated the importance of CD44 in esophageal squamous carcinoma demonstrating a higher expression of CD44v6, but its impact on tumor invasion remains controversial." (PMID 22069487, 2011). "CD44, an important α1, 2-FT-containing protein on cell surface, is involved in the adhesion and metastasis of tumor cells, and plays an important role in tumor progression." (PMID 21294926, 2011). "E-cadherin negatively regulates the interaction of CD44 with hyaluronic acid resulting in a suppression of tumor invasion and cell branching morphogenesis." (PMID 22069487, 2011). "CD44 expressed on the surface of cancer cells has been shown to facilitate binding to endothelial P- or L-selectin and increase tumor access to hematogenous spread." (PMID 21819617, 2011). "These CD44+ tumor cells expressed basal cell markers, cytokeratin 5 and 14, and the stem cell gene BMI1, consistent with a progenitor function." (PMID 24212622, 2011). "An animal model experiment has demonstrated that blocking CD44 with antibodies and antisense oligonucleotides decreases the malignant activities of the tumor." (PMID 21749678, 2011). "Pilot studies indicated that CD44 overexpression in Du145-VP16 slightly increased tumorigenicity (tumor incidence was 1/4 vs. 4/6 in Du145-VP16/pBabe.GFP and Du145-VP16/pBabe.CD44, respectively)." (PMID 21935404, 2011). "Basal-like tumours were found to contain a higher proportion of cells with a CD44+CD24−/low or ALDH1+ phenotype whilst Her2-positive cancers predominantly contained ALDH1+ cells." (PMID 24212798, 2011). "We have previously found that recombinant CD44 HABD 21–132, as a model for soluble CD44, inhibited human subcutaneous tumor xenograft growth in mice, angiogenesis in chick chorio-allantoic membrane, and EC proliferation." (PMID 22216242, 2011).
tumor (continued). "CD44+/CD24- is considered a cancer stem cell or tumor initiating cell signature, and high CD44/CD24 ratios are characteristic of aggressive Claudin-low tumors and cell lines." (PMID 21931769, 2011). "One study found similar telomere length and telomerase activity in tumor initiating prostate cells (characterized by CD44, integrin α2β1 and CD133 markers) compared to the total cell population." (PMID 21827695, 2011). "In human colorectal cancer, the ability to engraft in vivo in NOD/SCID mice is restricted to EpCAMhigh/CD44+ tumor cells." (PMID 21858056, 2011). "CD44 is one of cell-surface glycoproteins which relates to cell-cell interactions including adhesion and migration, and thus to tumor growth and progression." (PMID 21888658, 2011). "Earlier examination of PC3 cells revealed a hierarchy in subpopulations of cells in culture for their tumorigenic capacity with holoclones expressing CD44 being stem-like cells with tumor initiating activity." (PMID 24212937, 2011). "CD44, one of important adhesive molecules on cells, is involved in the adhesion and metastasis of tumor cells and plays an important role in tumor development, but the regulatory mechanism is unclear yet." (PMID 21294926, 2011). "CD44 and P-glycoprotein encoded by the MDR-1 gene have a functional link, and collectively regulate malignant biological phenotypes, tumor invasion, and MDR." (PMID 21749678, 2011). "The fraction of CD44+ cells in the tumor was as high as 10%, and ∼5000 cells was required for tumor formation, suggesting that CD44+ cells are not a pure HNC stem cell population." (PMID 24212622, 2011). "As observed after 4-MU treatment, the remaining proliferative activity was confined to the CD44-positive circumference of tumour cell islands." (PMID 21429221, 2011). "The role of the expression of CD44 isoforms in tumor progression has been widely studied in the last decade." (PMID 21749678, 2011). "Both normal salivary gland and tumor salivary gland cells displayed CD44 staining via FACS analysis." (PMID 21858056, 2011). "Prospective knockdown of CD44 in Du145 cells inhibited cell proliferation and tumor regeneration, whereas restoration of CD44 expression in drug-tolerant Du145 cells increased cell proliferation and partially increased tumorigenicity." (PMID 21935404, 2011). "A small number of tumours with high expression of CD44 and CD133 showed pathological response to DCX-based neoadjuvant chemotherapy." (PMID 21829201, 2011). "A small number of tumours with high CD44 or CD133 expression in pretreatment biopsies nevertheless showed good pathological response to DCX-based chemotherapy." (PMID 21829201, 2011). "In a previous study, we showed that down-regulation of CD44 sensitized BCSCs to the anti-tumor agent doxorubicin." (PMID 22152097, 2011). "Regardless from our analysis, the majority of cells from each metatstatic tumor line express the CD44 molecule on their surface." (PMID 24212937, 2011). "In the current study, most of CD44+/CD24− or ALDH1+ cell-rich tumours belonged to the basal-like subtype, which accords with the several previous reports pointing to a relation between CSCs and the basal-like subtype." (PMID 21559013, 2011). "There were more tumours with a maximum Allred score of 8 for the CD44+CD24-/low phenotype than the other CSC markers (4% for CD44+CD24-/low and ≤1% for the other CSC markers)." (PMID 22112299, 2011). "Efforts to link CD44 to CSCs and tumor progression should consider the expression of various CD44 isoforms." (PMID 21957977, 2011). "The mean fluorescent intensities (MFI) for CD44 was significantly higher on tumor cells than on wildtype cells (84 vs. 7, p<0.05)." (PMID 21858056, 2011). "A higher proportion of CD44+/CD24− tumour cells and ALDH1 positivity was associated with higher histologic grade (P=0.002 and P=0.007, respectively) and ER negativity of tumour (P<0.001 and P<0.001, respectively)." (PMID 21559013, 2011).
tumor (continued). "One possibility is related to inefficient delivery of drugs such that they cannot reach all CD44+ cells in the tumor." (PMID 21935404, 2011). "CSCs can be further enriched using CD44+α2β1hi marker profile and PCa cell holoclones, in which most cells are CD44+α2β1hi, contain self-renewing tumor-initiating cells." (PMID 21935404, 2011). "We analysed the association between the changes of CD44+/CD24− and ALDH1+ tumour cell population and clinicopathologic characteristics of tumour after PST." (PMID 21559013, 2011). "Within the subgroup receiving AD regimen, CD44+/CD24− tumour cell proportions also increased significantly (P=0.017) and the grades of ALDH1+ tumour cells had a tendency to increase after PST (P=0.098)." (PMID 21559013, 2011). "Selective knockdown of CD44 resulted in a striking reduction of the metastasizing capacity of the highly metastatic tumor in a rat pancreatic adenocarcinoma model." (PMID 22190973, 2011). "For instance, those discovered in human breast tumors had a subpopulation of CD44+CD24−/low tumor cells, capable of initiating and sustaining tumor growth after they were xenografted into NOD/SCID mice." (PMID 21858056, 2011). "Specifically, the basal-like subtype had the highest proportion of CD44+/CD24− tumour cells and the highest frequency of ALDH1 positivity among the subtypes." (PMID 21559013, 2011). "Hyaluronic acid binds to the cell-surface molecule CD44, and this interaction plays an important role in development, inflammation, tumor growth, and the recruitment and activation of many immune cells into injured tissues." (PMID 22022512, 2011). "As a result, some arguments remain regarding the relationship between CD44 expression and tumor progression and metastasis." (PMID 21749678, 2011). "Using this strategy, high activity of the intracellular enzyme, aldehyde dehydrogenase (ALDH), and the cell surface markers CD133 and co-expressed CD44/CD24 have been shown individually shown to possess tumor-initiating properties in different studies." (PMID 21695188, 2011). "SPP1 is a ligand of CD44 that binds to αV-containing integrins and is important in malignant cell attachment and tumor invasion." (PMID 21333016, 2011). "Tumor cells with a CD44+/CD24− phenotype were shown to have CSC properties in a variety of solid tumors." (PMID 21304586, 2011). "VP16 and STS partially eradicate CD44+ Du145 cells and the resultant DTCs display only a partial reduction in tumor-initiating capacity." (PMID 21935404, 2011). "Previous research demonstrated that knockdown of CD44 in BCSCs sensitized them to the anti-tumor drug doxorubicin, suggesting that CD44 knockdown affected the stemness or differentiation of these cells." (PMID 22152097, 2011). "Different isoforms of CD44 have been described to be involved in metastatic spread in different tumor forms even if the results are contradictory." (PMID 21957977, 2011). "We suggest that the physiological relevance of these results is supported by findings that vimentin and CD44 are up-regulated on tumor endothelial cells, whereas vimentin has been proposed as a potential anti-angiogenesis target." (PMID 22216242, 2011). "It has been reported by the same group that during tumor progression the selection of CD44+, CD133+ cells with ALDH activity increases in number and reaches the crypt axis." (PMID 24212789, 2011). "The population of cancer stem cells (CSC) within the tumor biopsy represented by CD44+CD133+ cells has been shown to have a high incidence of metastasis and invasion." (PMID 20175927, 2010). "HE staining revealed that tumours derived from CD24−/low/CD44+ and unsorted cells showed a similar histology, namely, exclusively invasive patterns with a variety of morphologies and the stromal component." (PMID 19997106, 2010). "The tumors associated with increased P-LVD or I-LVD tended to have higher CD44 expression, higher tumor stage, and nodal metastasis." (PMID 20374665, 2010).
tumor (continued). "In contrast, tumours derived from control cells showed both invasive and differentiated patterns associated with a smaller stromal component than CD24−/low/CD44+ or unsorted cells." (PMID 19997106, 2010). "CD44 staining is decreased in the heterotransplant and cytospin in comparison with the original tumor biopsy." (PMID 20175927, 2010). "These tumour spheroid cells retain the expression of well-known cell surface markers, including CD133, CD166, CD44, and EpCAM, as well as other stem cell-associated proteins such as NES, BMI-1, and MSI-1." (PMID 20332776, 2010). "In vivo Serial Transplantation Experiments of CD44+ and CD44− Cells Sorted from H1299 Xenograft Tumor." (PMID 21124918, 2010). "HA continuously transits through the lymphatic system and is potentially involved in lymph node homing by CD44+ leukocytes and tumor cells." (PMID 20374665, 2010). "In multivariate analysis, P-LVD was independently correlated with LVSI, tumor stage and CD44 expression (P = 0.561)." (PMID 20374665, 2010). "A better understanding of the role of CD44 and its interaction with hyaluronan and other binding partners in tumor initiation and progression would be required to clarify its relation with patient outcome." (PMID 21124918, 2010). "A third point requiring clarification is concerning to the presence of highly expressing CD44 cells, being an additional significant factor related to hyaluronan that affects tumor progression." (PMID 20849597, 2010). "CXCR4 and SDF-1 are candidate factors that involved in the cross-talk of the tumor-niche interaction of CD44+CD24- cells." (PMID 20569497, 2010). "Since H1299 CD44+ showed the shortest latency of tumor formation, we dissociated H1299 primary tumor to demonstrate in vivo serial tranplantability." (PMID 21124918, 2010). "This study is one of the first to reveal the histone code and MBD profile at the promoters of CD44, Cyclin D2, GLIPR1 and PTEN in different tumour cells and associated changes after stimulation with methylation inhibitor 5-aza-CdR." (PMID 20565761, 2010). "The CD44+∶CD44− ratio of the primary tumor was 80.72∶17.0, and of the secondary tumor was 85.4∶12.53." (PMID 21124918, 2010). "We monitored tumour formation by in vivo imaging and found that the luciferase activities of the tumours derived from CD24−/low/CD44+ cell populations treated with DHMEQ were significantly decreased compared with that of untreated cell-derived tumours." (PMID 19997106, 2010). "The latency of tumor formation from 5,000 CD44+ cells was progressively shortened from 30 days of the first generation, to 21 days of the second and 14 days of the tertiary generation, respectively." (PMID 21124918, 2010). "In SCC showing moderate to well differentiation, CD44 was expressed much more strongly in the basal compared to maturing tumor cells, consistent with the expected stem cell niches." (PMID 21124918, 2010). "As shown by the tumor growth curve, the primary and serially transplanted tumors initiated from 50,000 CD44+ cells grew faster than 200,000 unsorted cells." (PMID 21124918, 2010). "MCF-7 CD24-/low/CD44+ tumor-initiating cells, grown as mammospheres, have previously been shown to be more resistant to ionizing radiation than the general population of MCF-7 adherent cells." (PMID 20525204, 2010). "The NEP N-terminus also affects tumor formation by competing with the hyaluronan receptor CD44 for Ezrin/Radixin/Moesin (ERM) binding thereby reducing the invasive capacity of cancer cells." (PMID 20957047, 2010). "The CD133 cell-surface marker was used to purify putative CSCs in several tumor types, with the exception of breast, prostate and head and neck carcinomas where CD44 was utilized instead." (PMID 24281098, 2010).
tumor (continued). "Amongst the surface markers studied, we have shown that CD44+ cells are enriched for tumor propagating capacity and CD44 is a potential CSC marker of NSCLC cell lines." (PMID 21124918, 2010). "Further investigations of the roles and mechanistic pathways of CD44 in tumor initiation and progression are required to validate its role in CSC maintenance and regulation, and provide further insight on its usefulness as a specific therapeutic target." (PMID 21124918, 2010). "This glycoprotein is involved in many cell-cell interactions, stemness and tumor development, in part via β-catenin and Wnt signaling activation of the CD44 gene transcription." (PMID 20630067, 2010). "Formation of spheroid bodies and in vivo tumor initiation ability were demonstrated in CD44+ cells of 4 cell lines." (PMID 21124918, 2010). "Further investigation is required to clarify the role of CD44 in tumor cell renewal and cancer propagation in the in vivo environment." (PMID 21124918, 2010). "The tumor suppressor merlin can bind to the cytoplasmic tail of CD44 and disrupts the interaction between ERM and CD44 and therefore inhibits Ras activation." (PMID 20361869, 2010). "We showed that cells derived from CD24−/low/CD44+ populations resulted in tumours larger than those of CD24+/CD44+ control populations." (PMID 19997106, 2010). "The ESA+CD44+CD24-/low cells had up to 100- to 1000-fold greater tumor-initiating capability than the MCF-7 cells." (PMID 21192833, 2010). "As compared to the CD44+CD24+ CSC subpopulation, ALDH+CD44+CD24+ CSCs showed stronger tumor-initiating capacity, a significant mesenchymal gene profile and higher correlation to metastasis." (PMID 24281178, 2010). "Other CSC markers, CD133 and CD24, correlated with invasiveness and differentiation in CRC, while CD44 expression was related to tumour burden." (PMID 21339979, 2010). "Alternatively, the co-expression on tumour cells of CD44, CD166, and EpCAM molecules, has been reported to identify the CSC pool more precisely than CD133 expression alone." (PMID 20606680, 2010). "The role of CD44 in CaP development and progression is controversial, with studies showing both tumour-promoting and tumour-inhibiting effects." (PMID 20736947, 2010). "Our results also suggest that CD44/CD133 are suitable markers for tumor-initiating cells in the MiaPaCa2 cell line." (PMID 19714243, 2009). "a group of genes identified as being differentially expressed in a population of tumor initiating cells (CD44+CD24-) as compared to normal breast epithelium." (PMID 19327144, 2009). "The CD44+CD24-/low cells represent a small subclass within the tumor but are considered to be the actual tumorigenic cells whereas the rest, called nontumorigenic, have little or no such ability." (PMID 19664271, 2009). "In vivo CD44 targeting by siRNA and by specific antibody results in anti-tumor activity in colon cancer xenografts and human acute leukaemia xenografts, respectively." (PMID 19240712, 2009). "Further, disruption of CD44/MMP-9 cluster formation had resulted in reduction of tumor invasiveness in vivo." (PMID 19290049, 2009). "This allows us to live-sort candidate CSC-fractions from the MPE-tumor mix on the basis of surface markers (CD44, c-MET, uPAR, MDR-1) or differences in xenobiotic metabolism (ALDH)." (PMID 19536353, 2009). "While additional work is needed to elucidate the biological significance of these proteins, CD24 and CD74 expressed only in small proportion of cells indicating tumor heterogeneity and subtypes of tumor initiating cells (CD24+/CD44+) present in HNSCC." (PMID 19602232, 2009). "In HBCx-8 few isolated strongly staining cells were observed in the well-vascularised tumour periphery with a progressive increase in CD44+ cells towards the hypoxic/necrotic central area." (PMID 19240712, 2009). "Participation of CD44 (hyaluronan receptor) and CD49f (α6 integrin) in invadopodia (tumor cells) or podosomes (immune cells) has been previously reported." (PMID 19829710, 2009).